CTBP1 (C-terminal binding protein 1)
Diseases named in the same sentence as CTBP1 in open-access papers (continued):
Sharing a sentence is not in itself a finding about the gene and the disease.
tumor (continued). "After tumor growth initiates, high CtBP1 expression might provide a worse prognosis to the patients." (PMID 26933806, 2016). "Nevertheless, our results suggest that miR-644a or its target CTBP1 could be a potential drug candidate which can simultaneously block primary tumor growth, metastasis, and finally sensitize cancer cells to several different drugs." (PMID 27409664, 2016). "Of the LOH events that significantly characterized CR patients, only one, located on chr.4p16.1 and spanning 1.2Mb, included - among the other genes located within this region - a putative tumour suppressor gene, CTBP1, which acts as a transcriptional co-repressor in several human cancers." (PMID 26575327, 2016). "miR-137 has been reported to target the CtBP1, a co-repressor of various tumor suppressor genes." (PMID 22703336, 2012). "In addition, FBXO32-mediated epithelial-mesenchymal transformation (EMT) enhances the expression of Snail and ZEB1 through CtBP1 ubiquitination in breast cancer, which not only promotes tumor metastasis, but also upregulates PD-L1 and attracts MDSCs, further weakening the anti-tumor immune response." (PMID 40534867, 2025). "Due to the oncogenic activity of Ctbp1 in tumor development, its pharmacologic targeting may come with double benefit, increasing functional effector persistence for immunotherapy, while impacting on tumor cell growth." (PMID 38490212, 2024). "Thus, our finding demonstrated that CtBP1 could promote in vitro proliferation, invasion and migration of tumour cells." (PMID 32910558, 2020). "However, whether HGSOC tumor progression is dependent on CtBP2 or its paralog CtBP1, is not well understood." (PMID 32332713, 2020). "Moreover, CTBP1 and MeS increased circulating tumor cells (CTCs) and metastasis in nude mice." (PMID 29568399, 2018). "CtBP1splice expression after reduction of full length CtBP1 could be important in tumor cells due to general functions recently been described for CtBP as CtBP1 was shown to be involved in Golgi morphogenesis by association to centrosomes and in vesicular trafficking." (PMID 19216735, 2009). "These functional experiments provide strong evidence that BOP1, CTBP1, DSE, PMSD10, and SRPK1 play key roles in LMS progression, acting as potential therapeutic targets to limit tumor invasion and metastasis." (PMID 40963856, 2025). "Functional validation experiments confirmed that BOP1, CTBP1, DSE, PMSD10, and SRPK1 promote LMS cell migration, invasion, and colony formation, further highlighting their role in tumor progression." (PMID 40963856, 2025). "CTBP1 promotes tumorigenesis mainly by regulating the transcription of related genes, including promoting EMT, tumor metastasis and Warburg, etc." (PMID 37138491, 2024). "Overexpression of HERC5, downregulation of CtBP1, or blockade of CtBP1 function with its inhibitors (NSC95397 and 4-methylthio-2-oxobutyric acid [MTOB]) significantly prevents CRC cell proliferation in vitro and tumor growth in vivo." (PMID 36771004, 2023). "The mechanism of miR-539-3p-mediated tumorigenesis was targeted SPARCL1, RNF2, CTBP1, or CDK14 and inhibited the expression of these proteins in tumor cells." (PMID 35303885, 2022). "These proapoptotic genes are all the known targets of CtBP1, suggesting that HIPK2 overexpression inhibited tumor growth mainly by inducing the expression of proapoptotic genes." (PMID 33613771, 2021). "CtBP1 interacted with human adenovirus E1A via a PLDLS motif and would be functional as a tumor suppressor." (PMID 34253710, 2021). "Sahu acknowledged that CtBP1 facilitates the epithelial‐mesenchymal transition (EMT) and then speed the progression of tumor development and metastasis." (PMID 32628820, 2020). "Based on CTBP1 role in PCa cell adhesion and EMT, we also recovered circulating tumor cells (CTCs) from the peripheral blood of these mice." (PMID 30931931, 2019).
tumor (continued). "An increased expression of CtBP2, but not CtBP1, was reported in a small cohort of tumor tissue samples (n = 28) compared to noncancerous bone tissue samples." (PMID 40038783, 2025). "Using previously reported signatures, we found that 3 weeks after chronic tumor-antigen stimulation, multiple T-bet-repressed/ZEB2-dependent MP genes, as well as T-bet-induced/ZEB2-independent TE genes, were significantly higher expressed in Ctbp1-KO cells." (PMID 38490212, 2024). "Ctbp1-KO T cells showed improved tumor-eliminating capacity post-chronic stimulation, but not in a resting condition, consistent with the chronic stimulation screen and extending the prioritization results." (PMID 38490212, 2024). "CTBP1 has been reported to be involved in tumor chemoresistance; its high expression led to the occurrence of EMT and promoted the invasion and migration of tumor cells." (PMID 36397058, 2022). "In addition, the characteristic elevated NADH level of cancer cells makes it possible for CTBP1 to bind to NADP with a high affinity, thus triggering a conformational change that leads to hyper-activity of both tumorigenesis and tumor progression." (PMID 33424926, 2020). "Second, CtBP1 depletion dramatically decreases breast orthotopic tumor growth in these mice independent of diet." (PMID 26933806, 2016). "Immunoblotting of lysates from each of these cell lines revealed that levels of CtBP1/2 and NAMPT were higher in PDAC cell lines compared with HPNE cells, suggesting that both CtBP and NAMPT enzymatic activities may be hyperactive in PDAC tumor cells compared with normal pancreatic ductal cells." (PMID 37707363, 2023). "The study also showed that intratumoral C-terminal-binding protein 1 (CtBP1) controls the transcription of aromatase (CYP19A), a key enzyme that converts androgens to estrogens, and was overexpressed with increased TRAMP-C1 allograft tumor growth in mice receiving a HFD." (PMID 31052319, 2019).
cancer (71 papers, 2011 to 2026). A tumor composed of atypical neoplastic, often pleomorphic cells that invade other tissues. "In mammals, the Sbno2 gene is associated with cancer cell proliferation and survival, while the Simc1 gene encoded protein, SIMC1, interacts with the CTBP1 protein, which is involved in the ability of cancer cells to evade cell-cycle checkpoints." (PMID 41481677, 2026). "Since its initial identification, CTBP1 has been implicated in a broad range of developmental and pathological processes, including cancer." (PMID 41972124, 2026). "Evidently, CTBP1 has been linked to several cancer hallmarks through transcriptional regulation such as increased cell survival, proliferation, migration/invasion and epithelial-to-mesenchymal transition (EMT)." (PMID 40362431, 2025). "A key pro-oncogenic function in which CtBP1/BARS has been implicated is the ability to promote cancer cell migration and invasion, which is related to CtBP1/BARS role in induction of EMT and metastasis." (PMID 38711119, 2024). "CtBP1, a well-established gene expression regulator, has been implicated in the metastatic behavior of cancer cells." (PMID 37762332, 2023). "Based on our previous works, the present study focused on a novel gene CtBP1, which is associated with “cancer hallmarks” and has been observed to promote tumorigenesis when overexpressed." (PMID 37762332, 2023). "CTBP1, a coregulator implicated in cancer and EMT, links the transcriptional effects of NICD to oxygen and nutrients and to sprouting angiogenesis." (PMID 23955600, 2013). "In luminal A cancer, low expression of CTBP1, HEY1, HEY2 was associated with worse OS." (PMID 41463075, 2025). "C-Terminal Binding Protein 1 (CtBP1) has been implicated in various cancers, including ESCC." (PMID 37762332, 2023). "Activation of the AR regulator HIPK2 (Homeodomain-Interacting Protein Kinase 2) by genotoxic stress triggers apoptosis in part through phosphorylation of CtBP1, which causes CtBP1 degradation; loss of this signaling could plausibly cause predisposition to multiple forms of cancer." (PMID 26485759, 2015). "In this review, we critically examine the current literature on CTBP1 structure, regulation, and function, with a particular focus on cancer biology." (PMID 41972124, 2026). "CTBP1 and CTBP2 (C-terminal binding proteins) play critical roles in transcriptional repression and are frequently implicated in cancer progression." (PMID 40362431, 2025). "Recent research has demonstrated that PCA exerts anti-cancer effects in BC cells via targeting CtBP1." (PMID 40076435, 2025). "Targeting the Rossmann fold of CtBP1/BARS with small molecules has been proposed as a potential anti-cancer therapy, aiming to disrupt its interaction with transcription partners and protein complexes involved in mitotic entry and transcriptional activities." (PMID 38711119, 2024). "Our results are consistent with previous studies demonstrating that CtBP1 promotes cell proliferation and inhibits apoptosis in cancer cells." (PMID 37762332, 2023). "CTBP1 induces a wide range of tumorigenic- and cancer-stem-cell-relative functions through transcriptional regulation of gene networks." (PMID 37240137, 2023). "CtBP1 has been shown to promote epithelial–mesenchymal transition, a process that plays a critical role in cancer metastasis, by repressing the expression of E-cadherin, which is a vital mediator of cell–cell adhesion." (PMID 37762332, 2023). "Recent studies have shown that CtBP1 is overexpressed in multiple cancers to profoundly influence cellular phenotypic plasticity and stem cell pathways, which drives epithelial-to-mesenchymal transition and causes genome instability." (PMID 37762332, 2023). "Transiently dual CtBP1/2 knockdown had been achieved by a 48-h swap of CtBP1/2 siRNA interference in CtBP1/2 stable knockdown cancer cells, and validated by western blot analysis." (PMID 34253710, 2021).
cancer (continued). "Overexpression of CtBP1 also affects genome instability by inhibiting the expression of BRCA1 (Breast cancer 1) and BRCA212." (PMID 33613771, 2021). "Our data show that cancer cells perturbed by genetic or chemical down-regulation of the CtBP1,2 proteins present significant transcriptional and metabolic plasticity." (PMID 34680207, 2021). "CtBP1 induced a wide range of pro‐tumorigenic and cancer stem cell relative functions through transcriptional regulation of gene networks in the nucleus." (PMID 34586741, 2021). "The CtBP proteins (CtBP1 and CtBP2) are upregulated in cancer, including BC, and are emerging important regulators of BC biology." (PMID 34201346, 2021). "CtBP1/2 knockdown induced cancer cell apoptosis, increased genetic instability, and enhanced the sensitivity to DNA damage agents, such as γ-irradiation and chemotherapy drug (Carboplatin and etoposide)." (PMID 34253710, 2021). "CtBP1 is involved in the transactivation of MDR1 (Multidrug Resistance 1) in human multidrug-resistant cancer cells." (PMID 32140068, 2020). "As cancer advances in a MeS context, CTBP1 expression and/or activity would increase, leading to the repression of miR-205-5p and the upregulation of ZEB1, kick-starting the EMT process." (PMID 30931931, 2019). "Previous studies have reported that c-Myc, c-Jun, HIF-1 and CtBP1 can positively modulate ABCB1 expression in cancers, leading to the development of drug resistance." (PMID 31249297, 2019). "By day 7, when the control cancer cells were becoming very confluent, all the Pinin and CtBP1 knockdown cell lines showed, with CtBP2-KD cells a lesser degree, excessive detachment from the culture plates." (PMID 26871283, 2016). "Given the intimate interactions between Pinin and CtBP proteins, it is not surprising that the RNA processing aberrations were also observed in CtBP1-KD and CtBP2-KD cancer cells." (PMID 26871283, 2016). "One gene was ESRP1, which has been found to be associated with Pinin in a previous study and whose expression was significantly upregulated in Pinin-KD and CtBP1-KD cancer cells in the present study." (PMID 26871283, 2016). "The Pinin knockdown cell lines shared significant overlap of differentially expressed genes and RNA splicing aberrations with CtBP1 knockdown and in a lesser degree with CtBP2 knockdown cancer cells." (PMID 26871283, 2016). "Another finding about the interaction between Pinin and CtBP proteins is that Pinin levels were reduced in both CtBP1-KD and CtBP2-KD cancer cells." (PMID 26871283, 2016). "Pinin co-localized and physically interacted with transcriptional corepressor C-terminal binding proteins, CtBP1 and CtBP2, in the nuclei of cancer cells." (PMID 26871283, 2016). "In HCC cells, p19Arf binds to CtBP1 to inhibit cancer cell infiltration." (PMID 38932279, 2024). "Furthermore, highlighting the importance of investigating potential links between CtBP1 and microtubule dynamics offers avenues for exploring novel resistance mechanisms and gaining a deeper understanding of CtBP1’s implications in cancer biology." (PMID 37762332, 2023). "Furthermore, our findings support previous research showing that CtBP1 knockdown enhances chemosensitivity in other cancer types." (PMID 37762332, 2023). "Additionally, the limited expression of CtBP1 in most adult tissues and its ability to reactivate developmental programs when markedly expressed make it an attractive target for cancer therapy." (PMID 37762332, 2023). "The study reported that cancer cells challenged by genetic or chemical down-regulation of the C-terminal binding proteins 1 and 2 (CtBP1,2) show significant transcriptional and metabolic plasticity regulating the crosstalk between their biochemical pathways and the cell’s demands." (PMID 35208267, 2022).
cancer (continued). "CtBPs(CtBP1/2) was determined to be transcriptional co-repressor and oncogene in human cancer." (PMID 35299743, 2022). "Increases in CtBP1 are particularly interesting as this transcriptional co-repressor has also been reported to contribute to the metabolic and phenotypic abnormalities in cancer and microglia cells." (PMID 33868271, 2021). "The γH2AX and RPA32 phosphorylation foci signals were employed as readout indicators to evaluate the impact of CtBP1/2 knockdown on the DNA damage and genomic stability in cancer cells, which were typical markers for DNA damage, genomic stability, and cell survival." (PMID 34253710, 2021). "CtBP1 functions as an oncogene and is overexpressed in a variety of cancers." (PMID 32140068, 2020). "An increase in CtBP1 expression levels promotes cellular proliferation in several cancers." (PMID 29879296, 2018). "Although using miRNAs as potential drugs could need longer time, small molecules targeting CTBP1 could act as potential drugs for cancer therapy in the near future." (PMID 27409664, 2016). "CtBP1/2 or a regulator of their activity could therefore be a promising target for cancer therapy." (PMID 32332713, 2020). "The level of APH1A, CTBP1, HEY1, HEY2, JAG2, NOTCH4 was significantly higher in cancer samples compared to the control group, while the concentration of DTX1 TLE2, TLE4 was below the detection threshold." (PMID 41463075, 2025). "Functional redundancy between CTBP1 and CTBP2 is supported by the Cancer Dependency Map (DEPMAP) database." (PMID 38748792, 2024). "Considering the differences, further therapeutic strategies can be selected based on the background expression levels of CTBP1 and YY1 in different cancer types." (PMID 37240137, 2023). "Moreover, CtBP1/BARS transcriptional activity promotes disordered cellular metabolism and cancer stem cell phenotype." (PMID 38711119, 2024). "CtBP1/BARS overexpression, in multiple cancers, has pro-tumorigenic functions regulating gene networks associated with “cancer hallmarks” and malignant behavior including: increased cell survival, proliferation, migration/invasion, epithelial-mesenchymal transition (EMT)." (PMID 38711119, 2024). "We reported that C-terminal binding protein 1 (CTBP1) depletion in androgen-insensitive PCa xenografts from HFD-fed mice modulated the expression of mRNAs and microRNAs (miRNAs) involved in cancer related pathways which impacts on PCa proliferation and invasion." (PMID 36387263, 2022). "Moreover, ZEB2 correlates with SMAD1 in 28 cancer types, SMAD2 in 27 cancer types, SMAD3 in 22 cancer types, SMAD5 in 28 cancer types, CTBP1 in 14 cancer types, and CTBP2 in 22 cancer types." (PMID 35723302, 2022). "As the repressor protein CtBP1 is considered as a therapeutic target in various cancer types and might have a role specifically for EVI1 overexpressing malignancies, these observations need to be considered when targeting CtBP1 interactions therapeutically." (PMID 32979164, 2020). "Ten total RNA samples, with two separate RNA preparations for each of the control, CtBP1-KD, CtBP2-KD, Pinin-KD1 and Pinin-KD2 cancer cell lines, were submitted for cDNA library preparation and massively parallel paired-end multiplex RNA sequencing and analysis as described in Materials and Methods." (PMID 26871283, 2016). "Notably, PH-Fibs (both bovine and human) exhibit persistent elevation in CtBP1 activity even without a hypoxic stimulus, suggesting a stable metabolic reprogramming similar to that seen in cancer cells that drives the activity of transcriptional repressors like CtBP1." (PMID 38891046, 2024). "Analysis revealed overexpression of APH1A, CTBP1, HEY1, HEY2, JAG2, NOTCH4 regardless of the cancer subtype." (PMID 41463075, 2025).